HTR3B (5-hydroxytryptamine receptor 3B)
Description:
Forms serotonin (5-hydroxytryptamine/5-HT3)-activated cation-selective channel complexes, which when activated cause fast, depolarizing responses in neurons.
Synonyms: 5-HT3B
Tractability: Small molecule: an approved drug acts on it; a high-quality ligand is known; it belongs to a druggable protein family. Antibody: UniProt places it where antibodies can reach, with high confidence; its Gene Ontology location is reachable by antibodies, with high confidence; UniProt predicts a signal peptide or a membrane-spanning region. PROTAC: ubiquitination databases record sites on it; a small molecule that binds it is known.
Target class: 5HT3 receptor; Ion channel; Ligand-gated ion channel
Safety:
Unwanted effects reported when the protein is acted on. In parentheses: how it was acted on, where the effect was seen, and who reports it.
have relapsed before 52 weeks of nicotine abstinence (source: ClinPGx)
heroin dependence (source: ClinPGx)
nausea (source: ClinPGx)
statin-related myalgia (source: ClinPGx)
Gene: Protein-coding gene on chromosome 11 (113,904,796 to 113,949,079, forward strand). Ensembl gene ENSG00000149305.
Subcellular location: Postsynaptic cell membrane; Cell membrane
Pathways (Reactome):
Neuronal System: Neurotransmitter receptors and postsynaptic signal transmission
Gene Ontology:
Molecular function: serotonin-gated monoatomic cation channel activity; extracellular ligand-gated monoatomic ion channel activity; ligand-gated monoatomic ion channel activity; monoatomic ion channel activity; transmembrane signaling receptor activity
Biological process: serotonin receptor signaling pathway; serotonin-gated cation-selective signaling pathway; transmembrane transport; calcium ion transport; monoatomic ion transmembrane transport; monoatomic ion transport
Cellular component: cell surface; plasma membrane; serotonin-activated cation-selective channel complex; neuron projection; synapse; transmembrane transporter complex; membrane; postsynaptic membrane
Genetic constraint (gnomAD): Loss-of-function variants: 26 observed, 29.76 expected, observed/expected ratio (o/e) 0.87, 90% interval 0.64 to 1.21. The upper end of that interval is the gene's LOEUF score, 1.21, which puts it in group 5 of 6, group 1 being the genes least tolerant of losing a copy. Missense variants: 409 observed, 439.13 expected, observed/expected ratio (o/e) 0.93, 90% interval 0.86 to 1.01. Synonymous variants: 169 observed, 176.15 expected, observed/expected ratio (o/e) 0.96, 90% interval 0.85 to 1.09.
Homologues: Orthologues: chimpanzee HTR3B (99% identical), macaque HTR3B (94% identical), pig HTR3B (80% identical), dog HTR3B (77% identical), guinea pig HTR3B (75% identical), mouse Htr3b (73% identical), rat Htr3b (72% identical), rabbit HTR3B (68% identical), tropical clawed frog htr3b (50% identical), zebrafish htr3b (47% identical). Paralogues in human: HTR3A (42% identical), HTR3E (28% identical), HTR3C (27% identical), CHRNA5 (26% identical), CHRNB3 (26% identical), CHRNA4 (24% identical), CHRNA2 (24% identical), CHRNA7 (24% identical), CHRNA6 (23% identical), CHRNB2 (23% identical), CHRNB1 (22% identical), CHRNA3 (22% identical), and 33 more.
Diseases named in the same sentence as HTR3B in open-access papers:
HTR3B is named in the same sentence as 22 diseases in open-access papers, as found by Europe PMC text mining. Sharing a sentence is not in itself a finding about the gene and the disease. The quoted sentences say what the papers report.
depression (7 papers, 2011 to 2025). "The aim of this study was to investigate the relationship between polymorphisms of the HTR3B gene and depression and its executive dysfunction in Chinese Han population." (PMID 36849934, 2023). "So far, there is no study exploring the relationship between the polymorphisms of HTR3B gene and cognitive dysfunction in patients with depression." (PMID 36849934, 2023). "In a 2019 study of 222 depressed and 147 healthy Russians, the rs1176744 polymorphism of HTR3B gene was also found to be significantly related with depression." (PMID 36849934, 2023). "First, we investigated the relationship between the HTR3B gene polymorphisms and depressive disorder." (PMID 36849934, 2023). "A clinical study found that the polymorphism of rs1176744 in HTR3B gene was related to major depression in women." (PMID 36849934, 2023). "For example, a polymorphism in the HTR3B gene (rs1176744) was correlated to major depression in Japanese women and bipolar disorder." (PMID 35047998, 2021). "Furthermore, Htr3a and Htr3b gene-related polymorphisms are associated with genetic predisposition to musculoskeletal pain, depression disorders, and increased psychological conditions of dementia in patients with AD." (PMID 39329756, 2024). "In our study, we found that the polymorphism of rs1176744 in HTR3B gene may be associated with depression, where individuals carrying A allele may be more likely to develop depressive disorder." (PMID 36849934, 2023). "Therefore, we conducted a case–control study to investigate the association between HTR3B gene polymorphisms and depression and its executive function in Chinese Han patients with major depressive disorder." (PMID 36849934, 2023). "We discovered that in the Chinese Han population, the polymorphism of rs1176744 in HTR3B gene may be associated with depressive disorder." (PMID 36849934, 2023). "Previous studies have shown that depression was associated with HTR3B gene." (PMID 36849934, 2023). "The polymorphisms of HTR3B gene may be associated with depression in Chinese Han population." (PMID 36849934, 2023). "Additionally, there is an association between depression and the SNP rs6296 of HTR1B, HTR2A rs6561333 with cocaine dependence, HTR3B rs11606194 over time to relapse after smoking cessation and with nicotine dependence, and HTR3B rs1176744 with alcohol and nicotine dependence." (PMID 39731452, 2025).
Myalgia (3 papers, 2019 to 2021). "SNPs in the HTR3B and HTR7 genes were significantly associated with the myalgia score and may affect the development of myalgia in statin-treated patients." (PMID 33731122, 2021). "A candidate gene study in 195 statin-treated patients, of whom 51 experienced at least probable myalgia, found that rs2276307 and rs1935349 in the 5-hydroxytryptamine (5-HT, serotonin) receptor genes (HTR), HTR3B and HTR7, respectively, were significantly associated with myalgia score." (PMID 31861911, 2019). "The distribution of HTR2A (rs9316233), HTR3A (rs1062613), HTR3B (rs1176744), SERT (5-HTTLPR) and COMT (rs4680) genotypes in 117 patients with TMD myalgia (16 men and 101 women)." (PMID 35047998, 2021).
alcohol dependence (2 papers, 2020 to 2023). Physical and psychological dependence on alcohol. "In addition, the HTR3A and HTR3B genes in the 5-HT3, age and education are closely related to alcohol dependence." (PMID 33108388, 2020).
bipolar affective disorder (2 papers, 2016 to 2022). "Although several studies have reported an involvement of polymorphisms in the HTR3A (rs1062613) and HTR3B (rs1176744) genes and psychiatric conditions, such as eating and bipolar disorders, relatively few have explored their role in pain conditions." (PMID 28002447, 2016). "Furthermore, the HTR3B variant p.Tyr129Ser (rs1176744) has also been associated with bipolar affective disorder and female major depression as well as pain catastrophizing, a coping style characterized by excessively negative thoughts and emotions related to pain." (PMID 36121467, 2022). "With respect to the HTR3B gene, the SNP (rs1176744) was correlated to major depression in Japanese women and to bipolar disorders." (PMID 28002447, 2016).
Nausea (2 papers, 2020 to 2021). A sensation of unease in the stomach together with an urge to vomit. "The nodose also has a high degree of enrichment for the ionotropic serotonin receptors Htr3a and Htr3b, which are the pharmacological targets of antiemetic and anti-nausea drugs such as ondansetron." (PMID 33424545, 2020). "The objective for this study was to investigate whether MTX-induced nausea was associated with selected SNPs in candidate genes encoding MTX transporter proteins (SLCO1B1, SLCO1B3, SLC19A1, ABCB1, ABCC2), the MTHFR enzyme (MTHFR) and the 5-HT3-receptor (HTR3A, HTR3B), in children with JIA." (PMID 33794950, 2021).
nicotine addiction (2 papers, 2022 to 2025). "Moreover, HTR3B rs1176744 is also associated with alcohol and nicotine dependence." (PMID 39731452, 2025). "The results found in Chinese Han smokers further indicate the interaction of HTR3A and HTR3B genes in nicotine addiction." (PMID 35457612, 2022). "The authors of this study also analyzed the HTR3B and 5HTT genes, concluding that interactions between the three serotonergic genes may represent interacting biological effects of nicotine on fast-acting serotonergic signaling in nicotine addiction." (PMID 35457612, 2022).
alcohol use disorders (1 paper, 2013). "Although the functional consequences of the HTR3B variant rs3782025 are unclear this polymorphism has been associated with vulnerability to alcohol use disorders (AUD), another condition that has been suggested to be affected by 5-HT dysfunction." (PMID 23786674, 2013).
breast carcinoma (1 paper, 2023). "The genetic alteration of HTR1D, HTR3A, HTR3B, and HTR6 in breast cancer patients was significantly associated with shorter overall survival (OS)." (PMID 37795441, 2023).
heroin addiction (1 paper, 2025). "The intronic SNP rs11606194 of HTR3B is related to heroin addiction in European Americans." (PMID 39731452, 2025).
motion sickness (1 paper, 2021). sympton caused by motion, as sea sickness, train sickness, car sickness, air sickness, or space motion sickness. "To find predictive factors, we investigated the association of ADRA2A rs1800544 and HTR3B rs3758987 with motion sickness susceptibility and examined their mRNA changes during actual voyages." (PMID 34948773, 2021).
psychological distress (1 paper, 2021). "One was positively correlated to the HTR3B gene, jaw function and self-reported parafunctions, and the other was positively correlated to psychological distress and negatively correlated to SERT." (PMID 35047998, 2021).
schizophrenia (1 paper, 2020). A major psychotic disorder characterized by abnormalities in the perception or expression of reality. "The present paper describes the results of an association study of in the end 24 polymorphic variants of HTR1A, HTR1B, HTR2A, HTR2C, HTR3A, HTR3B, and HTR6 genes with TD and two of its subtypes in 449 patients with schizophrenia." (PMID 32390801, 2020). "A set of 29 SNPs of genes of serotonin receptors HTR1A, HTR1B, HTR2A, HTR2C, HTR3A, HTR3B, and HTR6 was studied in a population of 449 Caucasians (226 females and 223 males) with verified clinical diagnosis of schizophrenia (according to ICD-10: F20)." (PMID 32390801, 2020).
cancer (4 papers, 2013 to 2022). A tumor composed of atypical neoplastic, often pleomorphic cells that invade other tissues. "Our results suggest that determining the genotype of these polymorphisms except for TACR1 and HTR3B can help to inform individually based medication for treating or preventing CINV using genomic information for the Japanese cancer patients." (PMID 27446594, 2016). "Studies have shown that SNPs in HTR3A and HTR3B encoding subunits of the 5-HT3-receptor are associated with impaired receptor function and nausea in adult cancer patients." (PMID 33794950, 2021). "Totally 8 SNPs in 3 genes, COMT, HTR3B, CHRM3 (rs1176744, rs3782025, rs1672717, rs165722, rs4680, rs4633, rs10802789, rs685550), were significantly associated with the interindividual differences in nausea and vomiting among cancer patients treated with opioids." (PMID 23766564, 2013).
HTR3B also shares sentences with these, for which no sentence is quoted: alcoholism (1 paper); Anxiety (1); cocaine dependence (1); cognitive deficits (1); dementia (1); epilepsy (1); irritable bowel syndrome (1); lung carcinoma (1); lymphoma (1).